DSP (desmoplakin)
Description:
A component of desmosome cell-cell junctions which are required for positive regulation of cellular adhesion. Critical for cell-cell adhesion in early stage blastocysts and progression through proamniotic cavity formation (By similarity). Not required for preimplantation morphogenic process in blastocysts (By similarity). Required for keratin filament anchoring at the desmosome junction and subsequent organization of the keratin intermediate filament network within the cytoplasm (By similarity). Required for anchoring of desmosomes to the microtubule architecture, via its interaction with NIN (By similarity). Promotes microtubule-mediated GJA1/CX43 trafficking to cell membranes via its interaction with MAPRE1/EB1, thereby facilitating gap junction intracellular communication. Plays a key role in adhesion and organization of the dermal epithelial barrier. Critical for the maintenance of the neural tube structure following formation and organization of the neuroepithelium (By similarity). Facilitates outgrowth and repair of motor neuron fibers in regenerating axons following injury, probably by promoting recruitment of a complex containing DSP, CDH2, VIM and JUP to the outgrowth tips (By similarity). Critical for the normal formation of heart and myocardial tissue during early embryogenesis (By similarity). Also required for development of vascular capillary structures and intact endothelial cell barriers (By similarity). Regulates profibrotic gene expression in cardiomyocytes via activation of the MAPK14/p38 MAPK signaling cascade and increase in TGFB1 protein abundance (By similarity). Maintains cardiac rhythmicity by ensuring correct cell-cell adhesion within the sinoatrial node, via stabilization of protein components of both desmosome and Gap junctions (By similarity). Involved in maintaining the protein stability and recruitment of GJA1 to functional gap junctions, via inhibition of KRAS-mediated MAPK1/MAPK3 phosphorylation of GJA1 (By similarity). Negative regulator of cell cycle progression and differentiation in keratinocytes, potentially via inhibition of MAPK and phosphoinositide-3-kinase (PI3K) signaling pathways. Mediates the interaction between the desmosome and COP9 signalosome complex (CSN) protein complex. As a result of this interaction, promotes keratinocyte differentiation via deneddylation of EGFR resulting in a reduction in EGFR protein stabilization and translocation away from the cell membrane. Required for the maintenance of protein abundance of desmosome junction components DSG1, DSG2, DSC2, DSC3, PKP1, PKP2 and PKP3. Required for the survival and maintenance of germ cells in the gonads during embryonic development (By similarity). Binds to telomere DNA (via C-terminus) and acts to prevent telomere damage and maintain telomere length via its interaction with TRF2.
Synonyms: DP; KPPS2; PPKS2; DPI; DPII; DCWHKTA
Tractability: Small molecule: a structure with a bound ligand is known; it has a high-quality binding pocket. Antibody: its Gene Ontology location is reachable by antibodies, with high confidence; UniProt places it where antibodies can reach, with medium confidence. PROTAC: ubiquitination databases record sites on it; its protein half-life has been measured.
Gene: Protein-coding gene on chromosome 6 (7,541,326 to 7,586,717, forward strand). Ensembl gene ENSG00000096696.
Subcellular location: Cell projection, axon; Cell junction, desmosome; Cell membrane; Cytoplasm; Nucleus
Subcellular location (Human Protein Atlas): Cell Junctions
Pathways (Reactome):
Developmental Biology: Formation of the cornified envelope; Keratinization
Signal Transduction: RND1 GTPase cycle; RND3 GTPase cycle
Immune System: Neutrophil degranulation
Programmed Cell Death: Apoptotic cleavage of cell adhesion proteins
Gene Ontology:
Molecular function: protein binding; protein kinase C binding; RNA binding; scaffold protein binding; cell adhesive protein binding involved in bundle of His cell-Purkinje myocyte communication; structural constituent of cytoskeleton; structural molecule activity
Biological process: bundle of His cell-Purkinje myocyte adhesion involved in cell communication; cell-cell adhesion; epithelial cell-cell adhesion; keratinocyte differentiation; negative regulation of cell cycle; negative regulation of cell differentiation; peptide cross-linking; positive regulation of keratinocyte differentiation; positive regulation of protein localization; protein stabilization; regulation of heart rate by cardiac conduction; regulation of ventricular cardiac muscle cell action potential; telomere maintenance; desmosome maintenance; desmosome organization; epidermis development; establishment of endothelial barrier; germ cell development; intermediate filament cytoskeleton organization; intermediate filament organization; neural tube patterning; positive regulation of vasculogenesis; protein localization to cell-cell junction; regulation of protein localization; skin development; and 2 more
Cellular component: cell junction; cornified envelope; cytoplasm; desmosome; extracellular exosome; intercalated disc; nucleus; plasma membrane; adherens junction; axon; ficolin-1-rich granule membrane; intermediate filament; basolateral plasma membrane; cell-cell junction; cytoskeleton; fascia adherens
Genetic constraint (gnomAD): Loss-of-function variants: 115 observed, 302.83 expected, observed/expected ratio (o/e) 0.38, 90% interval 0.32 to 0.44. The upper end of that interval is the gene's LOEUF score, 0.44, which puts it in group 1 of 6, group 1 being the genes least tolerant of losing a copy. Missense variants: 3,230 observed, 3,669.8 expected, observed/expected ratio (o/e) 0.88, 90% interval 0.85 to 0.91. Synonymous variants: 1,311 observed, 1,387.7 expected, observed/expected ratio (o/e) 0.94, 90% interval 0.9 to 0.99.
Gene-disease validity (ClinGen):
ClinGen rates the evidence that DSP causes each of these diseases.
arrhythmogenic cardiomyopathy with wooly hair and keratoderma (autosomal dominant): Definitive. A cardioectodermal syndrome that is often associated with the gene DSP, encoding desmoplakin.
hypertrophic cardiomyopathy (autosomal dominant): Disputed. A condition in which the myocardium is hypertrophied without an obvious cause.
Homologues: Orthologues: chimpanzee DSP (99% identical), macaque DSP (99% identical), dog DSP (96% identical), rat Dsp (95% identical), mouse Dsp (95% identical), rabbit DSP (94% identical), pig DSP (93% identical), guinea pig DSP (93% identical), tropical clawed frog dsp (66% identical), zebrafish eppk1 (20% identical). Paralogues in human: PLEC (36% identical), MACF1 (18% identical), DST (18% identical), EPPK1 (16% identical), SYNE1 (12% identical), DMD (10% identical), SYNE2 (10% identical), UTRN (10% identical), PKHD1L1 (7% identical), SPTBN1 (7% identical), SPTBN5 (7% identical), FLNC (7% identical), and 24 more.
Diseases named in the same sentence as DSP in open-access papers:
DSP is named in the same sentence as 207 diseases in open-access papers, as found by Europe PMC text mining. Sharing a sentence is not in itself a finding about the gene and the disease. The quoted sentences say what the papers report.
cardiomyopathy (93 papers, 2016 to 2026). A disease of the heart muscle or myocardium proper. "Pathogenic variants in the DSP gene represent the most penetrant genetic drivers of arrhythmogenic cardiomyopathy, a mechanically uncoupled cardiomyopathy characterized by biventricular transmural fibroadipocytic replacement." (PMID 41561115, 2025). "Among these, 2 families were diagnosed with variants in DSP, a gene known to be related to cardiomyopathy as well as PPK." (PMID 39630431, 2025). "A ring-like LGE pattern has also been reported, although less frequently than in cardiomyopathies associated with DSP or FLNC mutations." (PMID 40869437, 2025). "DSP variants are associated with adverse outcomes compared to non-DSP variants and female sex is an adverse prognostic marker in DSP cardiomyopathy, potentially identifying a higher risk sub-group of female patients with DCM9." (PMID 40738566, 2025). "To enhance our understanding of the pathomolecular mechanisms underlying cardiomyopathy development, we conducted an in-depth study of a heart explanted from a patient carrying the heterozygous DSP c.1705A>T variant." (PMID 40034852, 2025). "Patients with palmoplantar keratoderma due to DSP variants were found, which is important to identify because of an associated risk of cardiomyopathy." (PMID 39630431, 2025). "A subset of cardiomyopathies is caused by heterozygous and homozygous mutations in the DSP gene, encoding desmoplakin, a constituent of the desmosomes in the intercalated disks." (PMID 40608429, 2025). "Occasionally dominant DSP variants associated with a cardiomyopathy phenotype exhibit minor cutaneous abnormalities." (PMID 39877668, 2025). "Although additional cardiomyopathy gene mutations have been described in these myocarditis case series, DSP is the most common gene reported, especially among those with relatively intact left ventricular function." (PMID 38768074, 2024). "The Invitae Arrhythmia and Comprehensive Cardiomyopathy panel identified two pathogenic variants in the desmoplakin (DSP, c.5028_5031del) and plakophilin-2 (PKP2, c.1912C>T) genes, confirming the underlying genetic cause for her presentation." (PMID 39185139, 2024). "A cohort of 18 probands, characterized as heterozygotes for DSP variants by a target Next Generation Sequencing (NGS) cardiomyopathy panel, was analyzed." (PMID 36768812, 2023). "DSP variants have been recently reported to be causative of a form of cardiomyopathy characterized by recurrent myocardial injury episodes and left ventricular fibrosis." (PMID 36768812, 2023). "Cardiomyopathy caused by desmoplakin gene mutations represents a distinct form with a high prevalence of left ventricle involvement." (PMID 36212137, 2022). "Most of these variants (n=20/26 variants, 77%) were found in DSP (n=37 individuals, 70%), of whom 1 individual (3%) had heart failure and 1 (3%) was diagnosed with a cardiomyopathy." (PMID 36264615, 2022). "Arrhythmogenic cardiomyopathy (ACM/ARVC), one of the cardiomyopathies associated with desmoplakin hotspot variants, is a rare (1:2000–1:5000) inheritable disease." (PMID 34065787, 2021). "A mutation ‘hot-spot’ within the NH2-terminal third of the DSP protein (specifically, residues 299–515) is associated with both cardiomyopathies and skin defects." (PMID 34065787, 2021). "In the largest reported series of pathogenic DSP variant carriers, WH was shown to have high specificity in detecting subjects who will develop a cardiomyopathy." (PMID 34926342, 2021). "Isolated reports in toddlers homozygous or compound heterozygotes for DSP variants show that cardiomyopathy is clinically manifest with severe biventricular or predominant LV involvement leading to heart failure." (PMID 34926342, 2021). "A heterozygous DSP c.6310delA, p.(Thr2104Glnfs*12) variant was observed in ten Finnish probands with cardiomyopathy." (PMID 32005173, 2020).
cardiomyopathy (continued). "For the remaining MYH7 HCM samples, variants in the following other cardiomyopathy genes were also found: DSP, MHY6, NEBL, PSEN1, RBM20, and TTN." (PMID 32344918, 2020). "Mutations in DSP are associated with abnormal cell–cell junctions and cause cardiomyopathies and keratodermas." (PMID 31620175, 2019). "Researchers have associated mutations in the DSP gene with severe cardiomyopathy and sudden night-time death, as well as dermatitis and palmoplantar keratoderma." (PMID 29297313, 2017). "Some studies have linked genetic alterations in desmosomal genes to cardiomyopathies; specifically, desmoplakin (DSP gene) mutations have been implicated in DCM." (PMID 28934278, 2017). "DSP mutations can lead to arrhythmia-induced cardiomyopathy." (PMID 41479920, 2025). "We set out to determine whether the DDR pathways were activated and pathogenic in an established mouse model of desmoplakin (DSP) cardiomyopathy generated upon deletion of the Dsp gene in cardiomyocytes (Myh6-MerCreMerTam Dspfl/fl; Myh6-McmTamDspfl/fl)." (PMID 40608429, 2025). "Naxos disease variant (Carvajal syndrome) is a cardiocutaneous genetic disease caused by Plakoglobin and Desmoplakin gene mutation, and usually manifests with woolly hair, palmoplantar keratoderma, and cardiomyopathy, and are found to have a high risk for uncontrolled arrhythmia." (PMID 40108711, 2025). "Additionally, germline iASPP KO in mice impairs cellular integrity in the myocardium and causes cardiomyopathy, reminiscent of the phenotype observed for desmoplakin-deficient mice." (PMID 39695191, 2024). "Furthermore, there are several cardiomyopathy genetic variants including DSP which require careful risk stratification due to an increased risk of sudden cardiac death." (PMID 38638283, 2024). "Furthermore, probands I, II, and III also inherited additional heterozygous cardiomyopathy-associated mutations, including DSP c.7883T>C, SCN5a c.3577C>T, or MYH7 c.427C>T, respectively." (PMID 39253717, 2024). "The median age at cardiomyopathy diagnosis was in line with our previous study of the same DSP variant; by the age of 60, cardiomyopathy could be diagnosed only in half." (PMID 37008330, 2023). "Pathogenic variants in its major constituent desmoplakin (DP; gene DSP) may give isolated cardiomyopathy, skin fragility, palmoplantar keratoderma (PPK) or woolly hair (WH), but also a combination of these, like in Carvajal syndrome." (PMID 35325485, 2022). "Human genetic studies have provided added insight and identified human DSP variants to have a particular affinity to intermittent myocardial inflammatory episodes similar to myocarditis but encompassing a distinct cardiomyopathy associated with left ventricular dominant fibrosis and arrhythmias." (PMID 34765046, 2021). "DSP (desmoplakin) has been reported to be expressed in cardiomyopathy, but this gene might be linked with progression of T1D in patients with cardiomyopathy." (PMID 33827531, 2021). "Besides the hub genes of MYBPC3, MYH7, and DSP, these subnetworks also include several genes that have been implicated in cardiomyopathy, such as TPM1, ACTC1, DES, TCAP, JUP, and DSG2." (PMID 32344918, 2020). "However, based on molecular predicted consequences, it is possible to hypothesize that variants causing a loss of function of DSP are more likely to be implicated in a severe form of cardiomyopathy." (PMID 36768812, 2023). "Furthermore, a ring-like pattern of LGE could better identify primary cardiomyopathies, in particular those secondary to DSP and FLNC pathogenic variants." (PMID 37189393, 2023). "Genetic mutations and aberrant functions of DES, DSP, GJA1, and SMOC2 are implicated in cardiomyopathies through dysregulation of key cellular processes, including tissue remodelling, intercellular communication, and extracellular matrix regulation." (PMID 41275133, 2025).
cardiomyopathy (continued). "In conclusion, currently, research on the role and mechanism of PANpoptosis in DSP-related cardiomyopathy remains limited, further studies are required to elucidate its association with PANpoptosis." (PMID 41479920, 2025). "High-risk features for each cardiomyopathy phenotype (HCM, DCM, ARVC) and gene-specific (Filamin C (FLNC), desmoplakin (DSP), RNA binding motif protein 20 (RBM20)) high-risk features are elaborated on in Chapter 7 of the ESC guideline." (PMID 40227490, 2025). "This is particularly pertinent in genes with variable penetrance or dual-phenotypic overlap, such as FLNA (neurovascular/cardiac), DSP (aortic/cardiomyopathy), or PRDM5 (ocular/aortic)." (PMID 40981152, 2025). "DSP cardiomyopathy is an intriguing form of cardiomyopathy whose phenotype is more consistent with the activation of the pathways involved in inflammation, fibrosis, and cell death." (PMID 40608429, 2025). "Compared to cardiomyopathies caused by variants in DSP, PKP2, FLNC, and LMNA genes, TTN-CMP and sarcomeric gene-related cardiomyopathies tend to exhibit a similar burden of HF events but a generally lower arrhythmogenic profile." (PMID 41329234, 2025). "Shortly after, the recessive DSP 7901delG variant was discovered in 6 patients from 3 Ecuadorian families, underlying a phenotype of PPK and WH similar to Naxos disease, but with a cardiomyopathy phenotype more closely resembling DCM." (PMID 39877668, 2025). "These genes are described for being important for cardiac function and related cardiomyopathies directly linked to gene defects/mutations or genetic variation within these genes (DES, DSP, GJA1)." (PMID 41275133, 2025). "Desmoplakin (DSP) cardiomyopathy is a form of arrhythmogenic cardiomyopathy (ACM) characterized by potentially fatal arrhythmias and episodic cardiac myocyte injury leading to ventricular fibrosis." (PMID 41573482, 2025). "Emerging evidence indicates that PANoptosis is closely associated with cardiomyopathy-related injury, with confirmed involvement in multiple myocardial pathologies including ICM, SCM, CIC, DCM, DSP-related cardiomyopathy, pathological hypertrophy and HF." (PMID 41479920, 2025). "Ring-like mid-wall or subepicardial LGE is suspicious for Desmoplakin (DSP) or Filamin C (FLNC) cardiomyopathies." (PMID 40429571, 2025). "A multidisciplinary evaluation and genetic testing revealed a heterozygous deletion in the desmoplakin (DSP) gene, confirming the diagnosis of desmoplakin cardiomyopathy." (PMID 40620837, 2025). "It was demonstrated that children with acute myocarditis have significantly more frequent mutations in genes associated with various cardiomyopathies, such as BAG3, DSP, PKP2, RYR2, SCN5A, and TNNI3." (PMID 39858598, 2025). "Desmoplakin (DSP) cardiomyopathy is an inherited left-dominant arrhythmogenic cardiomyopathy associated with heart failure, epicardial ventricular fibrosis, and ventricular arrhythmias (VA)." (PMID 39129740, 2024). "Case Series: The first case demonstrates a common phenotypic presentation of desmoplakin cardiomyopathy manifested as recurrent myocarditis and myocardial injury representing the hot phase." (PMID 38510230, 2024). "This evidence underlines the importance of differential diagnosis between acute myocarditis, ACM, and desmoplakin cardiomyopathy, although this can be difficult due to the genetic and phenotypic overlap of these conditions." (PMID 39336825, 2024). "Myocarditis has been recently included within the typical phenotype of desmoplakin cardiomyopathy, where VA and recurrence of acute myocarditis are frequently associated." (PMID 37189393, 2023). "For Arrhythmogenic Cardiomyopathy, there are 120 variations with contradictory interpretations; 83 of these 120 variations are located in the DSP gene, a relevant gene when studying cardiomyopathy disorders." (PMID 37946154, 2023).